IL6 (interleukin 6)
Diseases named in the same sentence as IL6 in open-access papers (continued):
Sharing a sentence is not in itself a finding about the gene and the disease.
Obesity (continued). "Other studies have shown that inflammatory cytokines known to be elevated in obesity (e.g. IL1β, TNF-α, and IL6) impair lymphatic collecting vessel contraction capacity, and, in the case of IL1β, do so by induction of iNOS expression." (PMID 26796537, 2016). "It is well known that obesity is a chronic inflammatory status with increased serum levels of tumor necrosis factor-α (TNF-α), interleukin-6 (IL-6), and IL-1β." (PMID 27070576, 2016). "In an in vitro model of obesity, 3T3-L1 adipocytes stimulated by LPS and RAW-CM presented increased IL-6 gene expression, as well as TNF-α and IL-6 cytokine production, but decreased peroxisome proliferator-activated receptor (PPAR)γ gene levels." (PMID 27983683, 2016). "Since IL-15 is induced by inflammatory stimuli, and several inflammatory cytokines such as IL-6, TNFα, IFNγ are implicated in promoting obesity and insulin resistance, we postulated that IL-15 might contribute to the pathogenesis of obesity rather than conferring protection against it." (PMID 27684068, 2016). "The link between obesity and inflammation has been derived from the finding that proinflammatory cytokines tumor necrosis factor alpha (TNF-α) and interleukin 6 (IL-6) are overexpressed in obesity." (PMID 26829184, 2016). "The Ly6Chigh macrophages amplify the severity of obesity-induced inflammation and hepatic IR through the secretion of TNF-α and interleukin 6 (IL-6)." (PMID 27999564, 2016). "In this study we further explore the effects of chronic administration of IL-6 in WT mice in a situation of diet-induced obesity (DIO), a situation that already increases the endogenous circulating IL-6 levels and induces fatty liver." (PMID 27333268, 2016). "Obesity positively regulates osteoclasts functioning by upregulating the synthesis of RANKL, TNF-α, MCP1, IL-6, PTH and M-CSF while also downregulating ERα expression, thereby accelerating bone resorption." (PMID 27746742, 2016). "Both IL-6 and IL1B were identified as highly differentially co-expressed genes across tissues between MHO and MUO individuals, showing their potential role in obesity-induced disease development." (PMID 27907186, 2016). "It is well accepted that obesity has an inflammatory status, including an elevation of the proinflammatory cytokines, TNF-α, IL-1β, and IL-6 in adipose tissues and sera." (PMID 27095436, 2016). "IL-10 has anti-inflammatory properties and enhanced its production by adipose tissue in obesity is a defense mechanism of body to counter-regulate the pro-inflammatory actions of several inflammatory cytokines such as TNF-α, IL-6 and IL-8." (PMID 26909479, 2016). "Chemical messengers (e.g., TNF-α, IL-6, AGE, leptins) that are upregulated or downregulated as a result of obesity have been shown to act as negative regulators of osteoblasts, osteocytes and muscles, as well as positive regulators of osteoclasts." (PMID 27746742, 2016). "As obesity is a low-grade inflammation, and EA has shown to have an anti-obesity effect, we measured important inflammatory markers such as TNF-α, IL-6 and CRP, in our patients, during EA treatment." (PMID 27136447, 2016). "NAFLD pathophysiologic processes linking obesity enhanced circulating concentrations of pro-inflammatory cytokines and factors (e.g., TNF-α, IL-6 and IL-1β)." (PMID 27483220, 2016). "Obesity causes lipid accumulation in adipocytes, which activates c-Jun N-terminal kinase (JNK) and nuclear factor-kappa B (NF-κB) signaling pathways and might subsequently increase the production of proinflammatory cytokines such as tumor necrosis factor-alpha (TNF-α) and interleukin-6 (IL-6)." (PMID 26136779, 2015). "It follows that the balance of cytokines, given by proinflammatory (such as IL-1β, IL-6, TNF) and anti-inflammatory effector molecules (such as IL-10) depends on both ageing and obesity-related dietary patterns." (PMID 26421054, 2015).
Obesity (continued). "Inflammation due to obesity also involved increased levels of pro-inflammatory cytokines such as TNF-α, MCP-1 and interleukin-6 (IL-6)." (PMID 26308010, 2015). "Our observations provide an understanding into the complex mechanisms, including changes in Akt, TNFα, IL6 and MCP1 by which estrogen regulates obesity and insulin resistance." (PMID 26317527, 2015). "Studies suggest that obesity TLR4 signaling essentially depends on MyD88 expression and up-regulated NF-κB activity, with IL-6 and TNF-α pro-inflammatory cytokines increased expression." (PMID 26635627, 2015). "Therefore, it has been theorized that persistent IL-6 increases found in chronic inflammation and obesity may have detrimental effects, while transient increases in IL-6 found in lean, healthy individuals may play a physiological role in normal glucose homeostasis." (PMID 26549941, 2015). "In obesity, the expanding adipose tissue releases a large numbers of mediators, including TNF-α, IL-6, and MCP-1 as well as FFA, which can interfere with insulin signaling." (PMID 25816341, 2015). "Transcripts altered by a Western diet that were examined in FHS were also compared to circulating levels of CRP and IL6, inflammatory markers shown to be increased in individuals with CVD, obesity, and a Western diet." (PMID 26148065, 2015). "On the other hand, adiponectin is inversely correlated with obesity and has a protective effect against insulin resistance as it exhibits anti-inflammatory properties by reducing TNF-α and IL-6 secretion from macrophages." (PMID 26003803, 2015). "Obesity and IR can lead to elevated levels of pro-inflammatory cytokines (e.g., TNF-α, IL-6, IL-1b, etc.) in both the peripheral and central nervous system of humans (T2DM:) and animals." (PMID 26340637, 2015). "In the present study, obesity induced an increase in the serum concentrations of TNF-α, IL-6 and IL-1β in the ob/ob group." (PMID 26714835, 2015). "In addition, obesity may also induce chronic low-grade inflammation resulting in an alteration of local and systemic levels of cytokines (e.g., interleukin-6, C-reactive protein) and adipokines (e.g., leptin, adiponectin), which may play a role in bladder carcinogenesis to bladder cancer mortality." (PMID 25803438, 2015). "Realizing that obesity is a chronic inflammatory state, we also explored the baseline and post-intervention levels of cytokines such as TNF-alpha, IL-6, IL-10, and PAI-1." (PMID 26611872, 2015). "Our data demonstrated several new findings on the expression of IL-6, IL-8, and MCP-1 under obesity-mimicking conditions." (PMID 25926797, 2015). "Obesity induces the activation of proinflammatory signaling in ATMs, resulting in upregulation of pro-inflammatory cytokines (i.e., TNF-α, IL-6 and inducible nitric oxide synthase (iNOS)), which act locally, contributing to IR14." (PMID 26459940, 2015). "Comparison between obesity and control groups regarding routine laboratory tests and levels of inflammatory mediators (TNF-α, IL-6, hsCRP) pre acupuncture (mean ± SD)." (PMID 27275202, 2015). "Despite the controversy regarding the differing effects of IL-6 as a cytokine and myokine, it continues to be studied as a marker of inflammation in HFD-induced obesity." (PMID 26185688, 2015). "Previous studies suggest there is low-grade inflammation in obesity along with altered levels of several circulating factors, such as increases in the plasma levels of TNF-α, CRP, IL-6, and other biological markers of inflammation." (PMID 26699936, 2015). "Comparison between obesity groups post acupuncture as regards routine lab analysis and inflammatory mediators (TNF-α, IL-6, hsCRP) (mean ± SD)." (PMID 27275202, 2015). "The two main findings are the negative impact of dyslipidemia, further worsened if hypertension and or obesity coexist, and inflammation markers (CRP and IL-6) on TL maintenance." (PMID 25799396, 2015).
Obesity (continued). "Increased concentration and expression of tumor necrosis factor-α (TNF-α), interleukin-6 (IL-6), and monocyte chemoattractant protein-1 (MCP-1) are evident in adipocyte dysfunction and insulin resistance in obesity and metabolic syndrome." (PMID 24932457, 2014). "We explored the relationship between age, eGFR, sex, obesity, LVH, hypertension, diabetes, smoking status, peripheral vascular disease or history of atrial fibrillation with TNFα, TNFR1, TNFR2 and IL-6 in the combined HF group." (PMID 24923671, 2014). "Obesity is underpinned by a chronic state of inflammation resulting from the increase in expression of inflammatory mediators such as TNF-α and IL-6." (PMID 25309775, 2014). "Depletion of CD8+ cells in obese mice decreased the number of macrophages in adipose tissue and lowered TNF-α and IL-6 levels, while T cell receptor (TCR)−/−mice were clearly protected against obesity-induced hyperglycemia and insulin resistance." (PMID 24823865, 2014). "The inflammatory process in obesity also involves other important cytokines, including classic ones such as TNF-α and IL-6, chemokines such as MCP-1 and MIP-1α, and proteins involved in vascular homeostasis such as the inhibitor plasminogen 1 (PAI-1)." (PMID 25324698, 2014). "Obesity increases the size and activity of adipocytes, leading to release of inflammatory molecules (e.g., IL-17, IL-22, TNF-α, IL-6, and monocyte chemoattractant protein 1 (MCP-1), tissue necrosis and subsequent accumulation of activated macrophages." (PMID 25548896, 2014). "Several studies have shown an important role of adipose tissue macrophages in inflammation in obesity through the production and release of proinflammatory mediators such as IL-1, TNF-α, IL-6, and CCL2." (PMID 24398136, 2014). "As SFRP5 does reduce production of proinflammatory TNFα, IL-6, and MCP-1, we expect it to exert anti-inflammatory effect in obesity related lung injury." (PMID 24899788, 2014). "For example, the levels of circulating fibrinogen and other acute phase reactants, including TNF, IL-6, and C-reactive protein (CRP) were found to be elevated in obesity." (PMID 25309773, 2014). "Psoriasis and obesity share similar mediators of inflammation, mainly tumor necrosis factor-α (TNF-α) and interleukin-6 (IL-6)." (PMID 24159327, 2013). "Capsaicin also attenuates obesity-induced inflammatory responses by reducing TNF-α, IL-6, IL-8, and MCP-1 levels, while enhancing adiponectin levels, important for insulin response." (PMID 23698776, 2013). "As a result, obesity is now recognized as a state of low-grade systemic inflammation characterized by high circulating levels of inflammatory molecules, such as TNF-α, IL-6, and C-reactive protein (CRP)." (PMID 24324381, 2013). "There is reduced skeletal muscle IL-6 receptor expression in obesity and abnormal STAT3/suppressor of cytokine signaling 3 (SOCS3) signaling, and attenuated IL-6 induced AMPKα2 activation with T2D." (PMID 23675368, 2013). "Obesity results in a chronic inflammatory state, and adipose tissue releases proinflammatory cytokines such as TNF and IL-6." (PMID 27335818, 2013). "An increase in plasma PAI-1 levels observed in obesity can also be the result of a cytokine-dependent induction of PAI-1 transcription where the proinflammatory cytokines such as IL-1, IL-6, and TNFα play the major role." (PMID 23819014, 2013). "The inflammatory mediators IL-6, IL-18, and CRP increase with age in both women and men and are highly correlated with obesity and degenerative disease." (PMID 23474627, 2013). "Fourth, obesity induces chronic low-grade inflammation resulting in an increase of local and systemic levels of cytokines (such as TNF-α, interleukin-6 (IL-6), C-reactive protein (CRP), and monocyte chemoattractant protein-1 (MCP-1))." (PMID 23431300, 2013).
Obesity (continued). "These macrophages are activated in the obese state and secrete IL-6, IL-1β, TNF-α and other pro-inflammatory cytokines, which contribute to a low-grade state of chronic systemic inflammation in obesity." (PMID 24025484, 2013). "This inflammation is characterized by increased serum concentrations of C-reactive protein (CRP), interleukin 6 (IL-6), IL-8, monocyte chemotactic protein-1 (MCP-1), and tumor necrosis factor alpha (TNFα) in patients and different animal models of obesity." (PMID 23819063, 2013). "Increasing obesity will lead to increased production of adipocytokines like TNF-α, IL-6 that lead to perpetuating cycle of JNK, and NF-κB activation leading to worsening insulin resistance." (PMID 22792473, 2012). "Leptin can control the production and activation of pro-inflammatory cytokines such as IL-6 and TNF-α by macrophages, and is a key regulatory factor expressed in both zebrafish and mammalian obesity in lipid metabolism." (PMID 22947075, 2012). "Obesity leads to pro-inflammatory milieu characterised by increased levels of TNF-α, IL-6, leptin, angio-tensinogen, plasminogen activation inhibitor-1 and decreased adip-onectin levels which promote endothelial functions." (PMID 22726248, 2012). "Increased levels of IL-6, IL-1RA, sICAM-1 and E-selection in the “high” CRP group are reminiscent of subclinical systemic inflammation seen in obesity, metabolic syndrome or type 2 diabetes." (PMID 22448235, 2012). "The obesity-related adipose gene expression pattern was dramatically altered by the HF-FO diet, whereby expression of MCP-1, IL-6 and IFNγ mRNA levels were reduced and IL-10 mRNA expression was elevated, compared to HF." (PMID 23166761, 2012). "Patients with DM or obesity have increased circulating levels of inflammatory markers including C-reactive protein (CRP), tumour necrosis factor-alpha (TNF-α), interleukin-6 (IL-6), and ICAM-1." (PMID 22347666, 2012). "On the other hand, adipocyte hypertrophy with the development of obesity, subsequently resulting in secretion abnormalities of FFA and adipocytokines such as TNF-α and IL-6, which are involved in insulin resistance." (PMID 22348333, 2012). "It is now well established that in obesity, insulin resistance is, at least in part, mediated by cytokines produced in adipose tissue, such as TNF-α and IL-6." (PMID 22174491, 2011). "In models of diet-induced obesity and genetic obesity, the adipose tissue has increased expression of proinflammatory cytokines, such as TNF-α, IL-1, and IL-6." (PMID 21352586, 2011). "Obesity isassociated with increased SUA levels and overproduction ofinflammatory molecules like TNF- α and IL-6 by the white adipose tissue." (PMID 21625475, 2011). "Indeed, we found that the positive associations between anthropometric variables and OA were largely dependent on leptin (but not IL-6), suggesting that obesity may cause cartilage damage systemically through production of leptin in adipose tissue in females." (PMID 20482813, 2010). "Adipocytes have been shown to secrete large quantities of IL-6 as well as non-negligible amounts of TNFalpha and there is increasing evidence that leads us to suppose that adipocytes are highly implicated in the inflammatory phenomenon associated with the development of obesity." (PMID 20148136, 2010). "Many obesity-related factors are responsible, including increased blood levels of insulin/IGF, IL-6, TNF-alpha, and leptin, and decreased blood levels of adiponectin." (PMID 21103795, 2010). "In elderly subjects with diabetes or obesity, longer cumulative averages also resulted in the greatest effects on inflammation in a study of PM2.5 effects on CRP, IL-6, and white blood cells." (PMID 20056584, 2010). "IL-6, IL-1β and APOH were identified as regulatory factors involved in blood coagulation and platelet activation in zebrafish and mammalian obesity." (PMID 20961460, 2010).
Obesity (continued). "Most of the remaining 21 are inflammatory proteins such as IL-8, PAI-1, MCP-1, IL-6, IL-1Ra, TNFα, sTNF RII, and IL-18 but the source of the elevated circulating levels in obesity is unclear." (PMID 20508843, 2010). "Thereafter, the concept was enforced by abundant literatureidentifying increases in many other inflammatory cytokines, such as plasmaC-reactive protein (CRP), interleukin 6 (IL-6), plasminogen activatorinhibitor-1 (PAI-1), in models of obesity." (PMID 20606248, 2010). "In the nvA(H1N1)-ARDS group, obesity and lymphocytopenia were more common and IP-10, interleukin (IL)-12, IL-15, tumor necrosis factor (TNF)α, IL-6, IL-8 and IL-9 were significantly increased versus control." (PMID 21062445, 2010). "In the present study,we examined whether resistin TNF-α, IL-6, and IL-1β mRNA levels from human peripheral mononuclearcells are altered in type 2 diabetes and whether they correlate withcirculating resistin levels and with indices of obesity or insulin resistance." (PMID 19125180, 2008). "It is interesting to note that PAI1 correlated significantly with all obesity variables (with BMI, 0.53; PBF, 0.51; WAIST, 0.56), IL6 (0.49), dyslipidemia, even with SBP and DBP, reaching almost the lowest but still significant correlation with fibrinogen." (PMID 18154661, 2007). "Obesity can induce a state of leptin and insulin resistance, chronic low-grade inflammation, and increased leptin, tumour necrosis factor (TNF)-α, IL-6 and C reactive protein serum levels." (PMID 16160698, 2005). "Therefore, we conducted a meta-analysis to examine the role of HIT on pro-inflammatory cytokines including C-reactive protein (CRP), interleukin 6 (IL-6), and tumor necrosis factor-alpha (TNF-α) in children with overweight/obesity." (PMID 41590696, 2026). "RT-qPCR results showed that, compared with the control group, mRNA expression levels of VEGFA, VEGFR-2, CD31, and SIRT1 were significantly decreased in the obesity group (P < 0.001), while the expression levels of GLUT1, HIF-1α, TNF-α, IL-6, HMGB1, and TLR4 were significantly upregulated (P < 0.01)." (PMID 41505418, 2026). "In obesity, there is a pronounced shift toward M1-like macrophage polarization in adipose tissue-evidenced by increased infiltration of TNF-α, IL-6, and monocyte chemoattractant protein-1 (MCP-1)-secreting macrophages-contributing to chronic inflammation and insulin resistance." (PMID 41556049, 2026). "In vitro studies have confirmed that betaine can inhibit the expression of hypoxia-induced IL-6 and tumor necrosis factor-alpha (TNF-α) mRNAs in human adipocytes, indicating that it directly acts on adipose tissue to reduce obesity-related low-grade inflammation." (PMID 41608511, 2026). "In patients with obesity, elevated blood levels of high‐sensitivity C‐reactive protein (hs‐CRP), tumor necrosis factor (TNF), and interleukin 6 (IL‐6) may increase local inflammation in periodontal tissues, thereby accelerating disease progression." (PMID 40955131, 2026). "In contrast, IL-1β and CCL2 reflect obesity-related inflammatory burden rather than early metabolic changes, while IL-6 and IL-15 did not reflect early metabolic alterations in this study." (PMID 42196825, 2026). "In obesity-related insulin resistance, hypertrophic adipocytes secrete elevated levels of pro-inflammatory cytokines, such as tumor necrosis factor-alpha (TNF-α) and interleukin-6 (IL-6)." (PMID 39940428, 2025). "Obesity may exacerbate systemic inflammation through increased production of adipokines and pro-inflammatory cytokines, such as TNF-α and IL-6, which have been suggested to play a role in the pathogenesis of either PsA or FM." (PMID 40572738, 2025). "Obesity is commonly considered a condition characterized bylow-grade chronic inflammation, in which macrophages in adipose tissue,especially in abdominal fat, are activated and release pro-inflammatory markerssuch as TNF-α, interleukin-6 (IL-6), and CRP." (PMID 40926826, 2025).